IRS4 (insulin receptor substrate 4)
Diseases named in the same sentence as IRS4 in open-access papers (continued):
Sharing a sentence is not in itself a finding about the gene and the disease.
liver cancer (3 papers, 2021 to 2023). An epithelial or non-epithelial malignant neoplasm that arises from the liver. "The population with lower levels of IRS-4 and Ki-67 had a higher risk of suffering from multifocal liver cancer (OR = 16.66; CI = 1.68–164.8 (95%); p < 0.05)." (PMID 34071030, 2021). "There was elevated nuclear expression of IRS4 in liver cancer and treatment of HEPG2 cell, a liver cancer cell line with IGF-1 and EGF-induced nuclear translocation of IRS4, stimulating cell proliferation by a β-catenin/Rb/cyclin D mechanism." (PMID 37686244, 2023). "In order to further evaluate a potential mechanism of IRS-4 action in liver cancer cells, we performed in vitro studies using HepG2 cells transfected with either the IRS-4 gene or with siRNA." (PMID 34071030, 2021). "Recently, our research group demonstrated the importance of IRS-4 in the development of liver cancer." (PMID 34577545, 2021). "In this investigation, we have evaluated the role of IRS-4 in a pilot study performed on patients with liver cancer." (PMID 34071030, 2021). "In the present study, we observed a bimodal effect of IRS-4, both in the proliferation and invasiveness of liver cancer." (PMID 34071030, 2021). "Collectively, our results suggest that the overexpression of IRS-4 may increase liver cancer growth, but its reduction together with Ki-67 could be important in the development in the multifocal phenotype." (PMID 34071030, 2021). "Interestingly, IRS-4 is overexpressed in both benign proliferative lesions, such as uterine leiomyomas and subungual exostosis, and malignant diseases, such as breast cancer, leukemia, lung cancer, colorectal cancer, and liver cancer." (PMID 34577545, 2021). "The present paper demonstrates for the first time the overexpression of nuclear IRS-4 in human HCC and its involvement in liver cancer cell proliferation as well in collagen cell adhesion and cell motility." (PMID 34071030, 2021).
T-cell acute lymphoblastic leukaemia (3 papers, 2009 to 2024). "However, IRS4 overexpression is associated with T-cell acute lymphoblastic leukaemia and subungual exostosis." (PMID 24039912, 2013). "In humans, point mutations of IRS4 and overexpressions of IRS4 due to chromosomal translocations, were recently identified in human paediatric T-cell acute lymphoblastic leukaemia and subungual exostosis, a benign tumour of bone and cartilage in the distal phalanges of fingers and toes." (PMID 24039912, 2013). "Irs-4 has also been implicated in the insulin-dependent proliferation of a murine T-cell lymphoma cell line and it is overexpressed in a pediatric T-cell acute lymphoblastic leukaemia (T-ALL) that harbors a breakpoint fusion between the T-cell receptor beta locus and the IRS-4 gene." (PMID 19534786, 2009). "In T-cell acute lymphoblastic leukemia and subungual exostosis, chromosomal translocation events promote the activation of IRS4 mRNA transcription." (PMID 39227585, 2024). "Notably, a mutant form of IRS4 (deletion from aa24–aa221, lacking the PH domain and putative NLS) was identified in a case of paediatric T-cell acute lymphoblastic leukaemia." (PMID 24039912, 2013).
colon cancer (2 papers, 2021 to 2022). "Similar results have been observed following overexpression of IRS-4 in RKO, a colon cancer cell line." (PMID 34071030, 2021).
Diabetes (2 papers, 2020 to 2023). "Men have a higher prevalence of diabetes than women, and high levels of insulin receptor substrate 4 and serum total cholesterol as well as elevated blood pressure are also associated with a higher risk of diabetes." (PMID 37894898, 2023).
Obesity (2 papers, 2017 to 2020). Accumulation of substantial excess body fat. "In humans, six SNPs in IRS4 have been identified that are associated with obesity, albeit in a cohort of patients with schizophrenia." (PMID 28257443, 2017). "Genetic deletion of Irs4 results in modest obesity and altered glucose homeostasis; whether this phenotype reflects simply a loss of Irs4 function or developmental compensation in response to Irs4 loss is unknown." (PMID 32218485, 2020). "Of interest, the IRS4 gene is involved in the IGF-1/growth hormone pathway and IGSF1 is associated with human obesity." (PMID 28257443, 2017). "Irs4-/y) developed severe obesity suggesting that IRS4 synergizes and complements IRS2." (PMID 28257443, 2017).
bladder cancer (1 paper, 2025). "In contrast, American patients with bladder cancer tend to harbor mutations that disrupt signaling by GPCR, with CDKN1A, IRS4 and KMT2D identified in the 6-gene set." (PMID 40768543, 2025).
breast tumours (1 paper, 2016). "To investigate whether high IRS4 expression was associated with survival, we examined a well annotated microarray data set obtained from a series of 157 human primary breast tumours from patients that developed metastatic disease." (PMID 27876799, 2016). "Collectively, our data demonstrate that IRS4 is expressed in a subset of human breast tumours and human cancer cell lines." (PMID 27876799, 2016). "Also in the human HER2+ breast tumour cell line BT474, in which ERBB2 is amplified, Irs4 expression had a strong effect on anchorage independent growth (P=0.0143, Welch's t-test)." (PMID 27876799, 2016).
gastric cancer (1 paper, 2024). A primary or metastatic malignant neoplasm involving the stomach. "Moreover, hsa_circ_0023409 promotes the progression of gastric cancer cells by activating the IRS4/PI3K/AKT pathway, thus facilitating gastric cancer cell progression." (PMID 39062792, 2024).
Glucose intolerance (1 paper, 2025). Glucose intolerance (GI) can be defined as dysglycemia that comprises both prediabetes and diabetes. "IRS-4 mRNA is found in skeletal muscle, liver, heart, brain, and kidney and IRS-4 KO mice had little growth retardation and glucose intolerance." (PMID 40141412, 2025).
Hepatitis (1 paper, 2013). Inflammation of the liver. "Neither was IRS4 expression increased in cells transfected to express the AAV viral coat protein, nor in HuH7 cells transfected with hepatitis C RNAs (data not shown)." (PMID 24039912, 2013).
hepatoblastoma (1 paper, 2021). Hepatoblastoma (HB) is a malignant hepatic tumor and is the most common pediatric liver cancer.
HIV-1 infection (1 paper, 2019). The type species of lentivirus and the etiologic agent of acquired immunodeficiency syndrome (AIDS). "Therefore, it would be interesting to investigate how USP18 impacts IFN-I signaling regulation during HIV-1 infection, and whether STAT2 and/or IRS-4 are involved." (PMID 31658294, 2019).
hypopituitarism (1 paper, 2025). A condition of diminution or cessation of secretion of one or more hormones from the anterior pituitary gland. "There are many causative genes for its isolated form or for multihormonal hypopituitarism, such as TSHβ, TRHR, TBL1X and IRS4 (for heritable isolated central hypothyroidism) and PROP1, HESX1, SOX3 (for multihormonal hypopituitarism)." (PMID 39997750, 2025).
hypothyroidism (1 paper, 2021). Abnormally low levels of thyroid hormone. "Examination of the IRS4 locus in FinnGen (R5) database revealed the strongest associations to a rare Finnish haplotype associated with thyroid disorders (p = 1.3e-7) and hypothyroidism (p = 8.3e-7)." (PMID 34093435, 2021). "Across all 2925 phenotypes studied in the FinnGen project, the strongest associations discovered were with thyroid disorders (p = 1.3x10-7) and hypothyroidism (p = 8.3x10-7), which were associated to a rare Finnish-enriched haplotype (tagged by SNP rs1452561670 20 kb downstream of IRS4)." (PMID 34093435, 2021). "To explore the role of IRS4 in both hypothyroidism and across the medical spectrum, we used the large FinnGen population study which in release 5 had integrated genome-wide genotyping and extensive medical history data from 218 792 Finns." (PMID 34093435, 2021).
Impaired glucose tolerance (1 paper, 2021). An abnormal resistance to glucose, i.e., a reduction in the ability to maintain glucose levels in the blood stream within normal limits following oral or intravenous administration of glucose. "IRS4 knock-out mice exhibit mild metabolic differences including lower blood glucose levels, impaired glucose tolerance and decreased fertility." (PMID 34093435, 2021).
leiomyomatosis (1 paper, 2016). A condition characterized by the presence of numerous small benign smooth muscle neoplasms located throughout the body. "Unlike XLAS, which is related to the loss of the α5 (IV) chains due to mutations in COL4A5, leiomyomatosis is considered to be caused by the upregulation of the IRS4 gene, which is located next to COL4A528." (PMID 27377778, 2016).
leukemia (1 paper, 2023). A malignant (clonal) hematologic disorder, involving hematopoietic stem cells and characterized by the presence of primitive or atypical myeloid or lymphoid cells in the bone marrow and the blood. "Similarly, it has been shown that IRS4 expression is regulated in solid tumors at the transcriptional level by cis-element hijacking in the regulatory regions of the gene or by translocation of IRS4 gene to a very active locus in leukemia." (PMID 37760618, 2023).
metastatic melanoma (1 paper, 2012). A melanoma that has spread from its primary site to another anatomic site. "Overall, in metastatic melanoma, the PI3K pathway is altered by somatic mutations in a wide array of genes including PIK3CA, MTOR, PIK3R1, PIK3R5, and IRS4." (PMID 22912864, 2012).
multiple myeloma (1 paper, 2013). "Lower, but detectable, levels of IRS4 were also seen in HuNS1 (multiple myeloma) and ES-2 (ovarian clear cell adenocarcinoma) cells." (PMID 24039912, 2013).
neural tumors (1 paper, 2025). "Overall, by comparing to PA, we identified subtype-specific pathways in neural tumors: PAK signaling (PTPRD and PDGFRB) in GBM, regulation of CFTR activity pathway (PPP2R1A, RABEP1) in MBL, and ERK signaling (IRS4 and ATM) in NBL." (PMID 40768543, 2025).
osteosarcoma (1 paper, 2024). A usually aggressive malignant bone-forming mesenchymal neoplasm, predominantly affecting adolescents and young adults. "In osteosarcoma cells and tissue samples, the protein levels of CK1γ2 and IRS4 are negatively correlated." (PMID 39062505, 2024). "It is noteworthy that in osteosarcoma cell lines, the CK1γ2-induced non-phosphorylatable mutant of IRS4 exhibits higher levels of p-Akt both in vitro and in nude mice, showing faster cell proliferation and tumor growth." (PMID 39062505, 2024).
ovarian carcinoma (1 paper, 2022). A malignant neoplasm originating from the surface ovarian epithelium. "Our previous observations have already demonstrated a retarded cell proliferation in IRS4-deficient ovarian cancer cells." (PMID 35550247, 2022). "We did observe a certain extent of growth defect rescue with cells re-expressing in the Y779F mutant of IRS4, but these cells still showed significantly delayed proliferation rate compared to the parental ovarian cancer cells." (PMID 35550247, 2022). "Meanwhile, we applied the CRISPR-Cas9 system to genetically knock out the IRS4 gene in those ovarian carcinoma-derived cell lines with high IRS4 expression, such as OVCAR-5 and OVCAR-3." (PMID 35550247, 2022). "To further evaluate the importance of tyrosine phosphorylation of IRS4, we re-expressed these Y to F mutants, along with the WT, in OVCAR-5 IRS4-KO ovarian cancer cells." (PMID 35550247, 2022). "FER-mediated PIK3R2 recruitment by insulin receptor substrate 4 (IRS4) is crucial to ovarian cancer cell proliferation in vitro and tumorigenesis in vivo." (PMID 35550247, 2022). "The association of IRS4 and PIK3R2 was also decreased in FER-deficient OVCAR-5 ovarian cancer cells." (PMID 35550247, 2022). "Aberrantly high expression of insulin receptor substrate 4 (IRS4) was inversely correlated with prognosis in patients with ovarian cancer." (PMID 35550247, 2022). "The result demonstrated that a lower expression of IRS4 was correlated to longer overall survival in patients with ovarian cancer." (PMID 35550247, 2022). "(C) Immunohistochemistry staining for IRS4 protein in normal ovaries (n = 10) and malignant ovarian carcinomas (n = 18) samples." (PMID 35550247, 2022). "In conclusion, IRS4 was significantly overexpressed in ovarian cancers and its upregulation was inversely correlated with survival and prognosis in ovarian cancer patients." (PMID 35550247, 2022). "In line with our findings in cell cultures, we observed a higher expression of IRS4 in ovarian cancer patient samples." (PMID 35550247, 2022). "In addition, we collected 10 cases of normal ovary samples and 18 cases of malignant ovarian carcinomas samples to further explore the expression differences in IRS4 by immunohistochemistry staining." (PMID 35550247, 2022). "We first used immunoblotting analysis to compare the expression level of the IRS4 protein between 2 human ovarian surface epithelial (HOSE) cell lines immortalized by the human papilloma viral oncogenes E6 and E7, and 14 ovarian carcinoma-derived cell lines." (PMID 35550247, 2022). "Consistently, we also observed a dramatic decrease of phospho-AKT in both OVCAR-5 IRS4-KO cells and OVCAR-3 IRS4-KD cells, indicating a tight correlation between PI3K-AKT pathway and ovarian cancer cell proliferation." (PMID 35550247, 2022). "As the key regulatory subunit of PI3K kinase, recruitment of PIK3R2/p85β onto IRS4 is required for PI3K-AKT signaling pathway activation and tumorigenesis in ovarian cancer." (PMID 35550247, 2022). "Encouraged by our previous results we attempted to delineate the molecular mechanism by which IRS4 regulates the AKT signaling pathway, and therefore the likely mechanism by which it regulates the cell proliferation of ovarian cancer." (PMID 35550247, 2022). "Insulin receptor substrate 4 (IRS4) was upregulated in certain ovarian carcinoma-derived cell lines and important for PI3K-AKT pathway activation and ovarian cancer cell proliferation." (PMID 35550247, 2022). "Compared to normal HOSE control cells, two ovarian carcinoma-derived cell lines, OVCAR-5 and OVCAR-3, showed evident upregulation of IRS4 protein expression." (PMID 35550247, 2022). "Using a proximity-based tagging system in ovarian carcinoma-derived OVCAR-5 cells, we determined that FER-mediated phosphorylation of Tyr779 enables IRS4 to recruit PIK3R2/p85β, the regulatory subunit of PI3K, and activate the PI3K-AKT pathway." (PMID 35550247, 2022).
ovarian carcinoma (continued). "Ectopic re-expression of IRS4, rather than an empty vector, restored the potential of cell proliferation in IRS4-KO ovarian cancer cells." (PMID 35550247, 2022). "Collectively, genetic ablation or pharmacological inhibition of tyrosine kinase FER in ovarian cancer cells leads to decreased global tyrosine phosphorylation and PIK3R2 recruitment of IRS4, which is consistent with our ectopic overexpression studies in HEK293FT cells." (PMID 35550247, 2022). "Next, we stably expressed ectopic IRS4 into those ovarian carcinoma-derived cell lines with no IRS4 expression, such as HEY and OVCAR-8." (PMID 35550247, 2022). "To further pursue the role of the kinase FER in phosphorylating IRS4 in ovarian cancer cells, we generated FER KO OVCAR-5 ovarian cancer cells by CRISPR-Cas9 and tested whether the global tyrosine phosphorylation of IRS4 would be affected upon FER loss." (PMID 35550247, 2022). "Overall, we revealed a kinase-substrate mode between FER and IRS4, and the pharmacological inhibition of FER kinase may be beneficial for ovarian cancer patients with PI3K-AKT hyperactivation." (PMID 35550247, 2022). "While ectopic overexpression of FER dramatically increased tyrosine phosphorylation and PIK3R2 recruitment of IRS4, CRISPR-Cas9 directed KO or pharmacological inhibition of the endogenous kinase in ovarian cancer cells remarkably reduced tyrosine phosphorylation and PIK3R2 recruitment of IRS4." (PMID 35550247, 2022). "FER-mediated phosphorylation of Tyr779 on IRS4 enhances recruitment of PIK3R2/p85β, the regulatory subunit of PI3K, and promotes PI3K-AKT signaling pathway, which eventually leading to cell proliferation and tumorigenesis in ovarian cancer." (PMID 35550247, 2022). "Furthermore, our results also suggested simultaneously targeting both IRS4-mediated PI3K-AKT and ERK pathways may deliver a more effective strategy to treat ovarian cancer." (PMID 35550247, 2022). "Therefore, in the absence of IRS4-mediated PI3K-AKT activation, OVCAR-5 ovarian cancer cells would upregulate ERK activity in a compensating manner, thereby enhancing survival and proliferative capacities." (PMID 35550247, 2022).
ovarian tumor (1 paper, 2022). "In accordance with the result from HPA database, the expression levels of IRS4 in ovarian tumor samples were significantly elevated compared to normal control samples." (PMID 35550247, 2022). "Consistent with KO studies in OVCAR-5 cells, loss of IRS4 in OVCAR-3 cells also led to growth retardation, highlighting the key role of IRS4 in maintaining ovarian tumor cell growth." (PMID 35550247, 2022). "This kinase-substrate regulatory mode between FER and IRS4, which leads to PIK3R2 recruitment and AKT activation, is critical for ovarian tumor cell growth." (PMID 35550247, 2022). "Rescuing IRS4-null ovarian tumor cells with phosphorylation-defective mutant, but not WT IRS4 delayed ovarian tumor cell proliferation both in vitro and in vivo." (PMID 35550247, 2022).
prolactinoma (1 paper, 2022). "Two additional genes, IGSF1 and IRS4, were massively and specifically overexpressed in the F6 prolactinoma." (PMID 35978432, 2022).
renal failure (1 paper, 2021). "In addition to the association to thyroid endpoint category in FinnGen one IRS4 missense variant (rs1801164) had a significant association to renal failure." (PMID 34093435, 2021).
thyroid disease (1 paper, 2021). "Furthermore, we demonstrate an association of IRS4 gene locus to a general thyroid disease risk in the FinnGen database." (PMID 34093435, 2021).
uterine leiomyosarcomas (1 paper, 2025). "To further assess the IRS4 expression in uterine leiomyosarcomas, we utilized a publicly available TCGA dataset including RNA and exome sequencing data from 27 uterine leiomyosarcomas." (PMID 41162745, 2025). "Exome sequencing data was available from two leiomyosarcomas that showed elevated IRS4 expression (1553 and 1556), and the data confirmed a COL4A5-COL4A6 deletion in both samples." (PMID 41162745, 2025). "We observed elevated IRS4 expression in 5 out of 51 (10%) leiomyosarcomas." (PMID 41162745, 2025). "Gene expression profiling revealed high IRS4 expression in 4/27 (15%) leiomyosarcomas." (PMID 41162745, 2025).